TNF (tumor necrosis factor)
Diseases named in the same sentence as TNF in open-access papers (continued):
Sharing a sentence is not in itself a finding about the gene and the disease.
rheumatoid arthritis (continued). "Also, a recent study reported that TQ exerts anti-inflammatory effects by reduction of TNF-α, TLR-2, TLR-4, and Interleukin-1 in rheumatoid arthritis." (PMID 32793594, 2020). "TNF-α significantly induced IL-33 mRNA expression and protein synthesis, and overexpression of IL-33 significantly increased TNF-α-induced IL-6, IL-8, and matrix metalloprotease (MMP)-3 in rheumatoid arthritis synovial fibroblast." (PMID 33490289, 2020). "Antibodies that inhibit tumor necrosis factor (TNF) such as adalimumab infliximab etanercept and golimumab have been used for over 20 years in severe cases of autoimmune diseases such as rheumatoid arthritis, inflammatory bowel disease or ankylosing spondylitis." (PMID 34513612, 2020). "Coincidently, a recent study of rheumatoid arthritis (RA) showed that the high responsiveness to IL-7 stimulation together with the synergy of IL-7 and M1-promoting factors (e.g., MIP-1b, TNF-a) can enhance the expression of joint myeloid IL-7R and further exacerbate arthritis." (PMID 32117217, 2020). "The significant pathways of up‐regulated DEGs that were mainly enriched included cytokine‐cytokine receptor interaction, rheumatoid arthritis, inflammatory mediator regulation of TRP channels, NOD‐like receptor signalling pathway, NF‐κB signalling pathway and TNF signalling pathway." (PMID 32391647, 2020). "Orally administered HY7801 regulates immune biomarkers, including TNF-α, IFN-γ, IL-17A, IL-10, and IL-12, and might be useful in the treatment of rheumatoid arthritis." (PMID 32384794, 2020). "In patients suffering from rheumatoid arthritis or enthesitis-related arthritis, the synovia and surrounding tissue has been shown to contain a significantly higher amount of RANKL and other pro-inflammatory cytokines (IL-17, IL-23, TNFα)." (PMID 32082321, 2020). "For instance, anti-TNFα antibodies, soluble TNF receptor 2-conjugated Fc domain of IgG1, anti-IL-6 receptor antibody, and an IL-1 receptor antagonist have exhibited dramatic effects on rheumatoid arthritis patients." (PMID 32079226, 2020). "Additionally, a significant decrease in the levels of IL-6, TNF-α and IFN-γ was found in patients with rheumatoid arthritis and psoriasis treated with itolizumab." (PMID 33292350, 2020). "This study confirms that stimulation with tumor necrosis factor (TNF-α) results in expression of proinflammatory genes in mouse and human FLS (derived from osteoarthritis and rheumatoid arthritis patients), as well as increased secretion of cytokines from mouse TNF-α-stimulated FLS (TNF-FLS)." (PMID 32332252, 2020). "Although at the time the rationale for anti-TNF therapy in rheumatoid arthritis was new and not widely accepted, several TNF-inhibitors were generated as a possible treatment for bacterial septic shock." (PMID 32174918, 2020). "TNF-α inhibitors (TNFi) such as infliximab (IFX), adalimumab (ADA), etanercept (ETN), golimumab, and certolizumab pegol are dramatically effective for the treatment of rheumatoid arthritis (RA)." (PMID 33315881, 2020). "On the other hand, there was another study of patients with rheumatoid arthritis and breast cancer that showed that TNFα-blockade did not increase recurrence of breast cancer with respect to patients treated otherwise." (PMID 32391269, 2020). "Moreover, in 50 rheumatoid arthritis (RA) patients, 500 mg quercetin supplementation during 8 weeks ameliorates clinical symptoms such as early morning stiffness and pain, disease activity, and TNFα plasma levels." (PMID 32050623, 2020). "Our findings are in agreement with previous reports that demonstrated CX3CL1, but not CXCL16 induction by TNF-α in rheumatoid arthritis synovial tissue fibroblasts." (PMID 33552057, 2020). "Rheumatoid arthritis is an autoimmune disease and is usually treated with TNF-α blockers, minocycline, azathioprine, and non-steroidal anti-inflammatory drugs." (PMID 32102185, 2020).
rheumatoid arthritis (continued). "Contradicting to initial postulations, the development of polyarthritis in A20myel-KO mice was not dependent on TNF, T lymphocytes, or B lymphocytes, which are involved in the pathogenesis of rheumatoid arthritis." (PMID 32958016, 2020). "Moreover, it has been documented that over-expression of miR-99b-5p brings about elevations in the expression levels of proinflammatory cytokines (IL-2, IL-6, TNFα, and IFN-γ), thus promoting the pathogenesis of rheumatoid arthritis." (PMID 33109608, 2020). "Activated macrophages could produce and release pro-inflammatory cytokines, such as TNF-α, IL-6, NO and PGE2, which thus played a key role in inflammatory diseases such as sepsis, rheumatoid arthritis, inflammatory bowel disease, psoriasis and Type 2 diabetes." (PMID 32031205, 2020). "Disease-modifying anti-rheumatic drugs (DMARDs) are the cornerstone of anti-inflammatory therapy in rheumatoid arthritis (RA), with patients who do not respond to traditional synthetic DMARDs usually initiating therapy with TNF inhibitors." (PMID 31647025, 2019). "Tumor necrosis factor-α (TNF-α) antagonists, most of which are monoclonal antibodies, became a widespread treatment for autoimmune diseases such as rheumatoid arthritis, ankylosing spondylitis, inflammatory bowel diseases, psoriasis, psoriatic arthritis, hidradenitis suppurativa and uveitis." (PMID 30732563, 2019). "There is also growing evidence that anti-TNF-α biological drugs used to treat rheumatoid arthritis (RA) can improve insulin sensitivity and reduce insulin resistance in RA patients, raising the possibility that targeting proinflammatory pathways may also have therapeutic benefits in T2DM patients." (PMID 30719343, 2019). "This was similar to the 2.0% rate of serious infections in infants of women with rheumatoid arthritis but no exposure to an anti-TNF-α medication in pregnancy who were ascertained from the same claims data sources." (PMID 31626646, 2019). "For instance, TNFα-induced dephosphorylation of FOXP3 at Ser-418 by protein phosphatase 1 (PP1) compromises Treg suppressive activity within the inflamed synovium, which is responsible for the pathogenicity of rheumatoid arthritis." (PMID 31681337, 2019). "Additionally, an alternative therapeutic application is to utilize CBCRs to target cytokines such as tumor necrosis factor-alpha (TNF-a) or IL-6, which are over-expressed in chronic inflammatory diseases (e.g., rheumatoid arthritis)." (PMID 31798579, 2019). "Current research in the management of rheumatoid arthritis is turning to a new generation of substances capable of selectively inhibiting TNF alpha and/or cyclooxygenase (COX-2) and having no major side effects." (PMID 31827550, 2019). "Biological therapies targeting TNF-α, T cells, B cells, and various cytokines (including IL-6 and IL-1) have become essential for the treatment of rheumatic diseases [mainly rheumatoid arthritis (RA), ankylosing spondylitis, and psoriatic arthritis], as well as other immune-mediated diseases." (PMID 31134083, 2019). "The goal of this study is to use comprehensive molecular profiling to characterize clinical response to anti-TNF therapy in a real-world setting and identify reproducible markers differentiating good responders and non-responders in rheumatoid arthritis (RA)." (PMID 31647025, 2019). "The objective of the present study was to evaluate the effects of Enalapril, Losartan and Valsartan on the production of IL-2, IL-10, IL-6, TNF, IFN-γ, IL-17A, IL-17F and IL-22 cytokines in PBMCs of patients with rheumatoid arthritis and evaluate this modulation with disease activity." (PMID 30288187, 2018). "Tumor necrosis factor (TNF) is an important human cytokine that is involved in a number of critical biological processes and diseases, including rheumatoid arthritis, Crohn’s disease, multiple sclerosis, inflammatory bowel disease, psoriatic arthritis, AIDS, and cancer." (PMID 30090063, 2018).
rheumatoid arthritis (continued). "In a rat model of rheumatoid arthritis, DPA showed a comparable reducing effect with EPA on the progression and severity of arthritic disease as well as pro-inflammatory cytokines, such as IL-17A, IL-1β, IL-6, and TNFα." (PMID 30347833, 2018). "Our patient was previously on etanercept, a TNF inhibitor, and rituximab for his rheumatoid arthritis but had not taken either medication for over a year." (PMID 29849657, 2018). "According to a recent report, there are no late-stage rheumatoid arthritis products targeting TNF under development." (PMID 30090063, 2018). "Similar was the result of a study including patients with active rheumatoid arthritis who showed marked insulin resistance, but this was not influenced by anti-TNF therapy despite a reduction in systemic inflammation after treatment." (PMID 29576769, 2018). "Tumor necrosis factor (TNF) is a pleiotropic pro‐inflammatory cytokine and a key mediator in many inflammatory disorders, such as inflammatory bowel disease (IBD) and rheumatoid arthritis (RA), as well as neurodegenerative diseases such as Parkinson's disease and AD." (PMID 29472246, 2018). "TNF-α and IL1 are the most widely used cytokines to induce OA as well as rheumatoid arthritis." (PMID 29783732, 2018). "However, aberrant TNF-α overexpression can induce chronic inflammation and subsequent tissue destruction and thus play important roles in various diseases including cachexia, Crohn's disease (CD), and rheumatoid arthritis (RA)." (PMID 29850502, 2018). "In rheumatoid arthritis, the substantial amount of soluble MIC released by synoviocytes failed to downregulate NKG2D on CD4+ T cells, possibly due to high levels of IL-15 and TNF-α." (PMID 30150983, 2018). "Treatment with anti-TNFα, a widely used therapy in patients with IBD, effectively modulates immune function in the gastrointestinal tract, and appears to reduce sickness behavior and depressive symptoms in IBD, rheumatoid arthritis and psoriasis." (PMID 29518097, 2018). "Aberrant upregulation and activation of pro-inflammatory cytokines and chemokines, including TNF-α, IL-1β, IL-6, IL-8, CCL5, and CXCL8, has been correlated with the progression of chronic inflammatory diseases, such as tumor, sepsis, rheumatoid arthritis, psoriasis, and cytotoxicity." (PMID 29045468, 2017). "On the other hand, TNF-α inhibition therapy brought a revolution in the treatment of several autoimmune diseases, such as rheumatoid arthritis, psoriasis and non-specific inflammatory bowel diseases." (PMID 28460644, 2017). "Since simultaneous inhibition of both the p38MAPK and ERK-MSK-CREB pathways are required to significantly reduce LPA-mediated IL-8 and IL-6 production in TNFα-preconditioned RAFLS, drug combinations targeting these two pathways are potential new strategies to treat rheumatoid arthritis." (PMID 29209219, 2017). "Over the last 5 years, several non-anti-TNF-targeted biologics have been licensed for the treatment of rheumatoid arthritis, ankylosing spondylitis, and psoriatic arthritis." (PMID 28659665, 2017). "In addition, there have been several recent reports of anti-TNF-α-induced AIH in patients treated for inflammatory bowel disease, rheumatoid arthritis, or psoriasis." (PMID 28184367, 2017). "Importantly, a recent large epidemiological study, in which administering regular subcutaneous etanercept, a specific anti-TNF biological agent in common clinical use, over an extended period in treatment of rheumatoid arthritis (RA), was reported to reduce incidence of AD in these patients." (PMID 28451786, 2017). "It has been well documented that adenosine and its receptors are able to suppress elevated levels of proinflammatory cytokines such as tumor necrosis factor α (TNF-α) and interleukin β (IL-β) released in the most common musculoskeletal diseases and rheumatoid arthritis." (PMID 28255202, 2017).
rheumatoid arthritis (continued). "Finally, the level of TNF-α in synovia has been correlated with pain and disease progression and anti-TNF-α agents have been widely used for the treatment of active rheumatoid arthritis." (PMID 28377922, 2017). "While monoclonal antibodies against TNFα, including Infliximab, have been used to treat autoimmune conditions such as rheumatoid arthritis, TNF-specific immunotherapies have not been deployed in VS." (PMID 29018206, 2017). "Early reports of increased expression of tumor necrosis factor (TNF)-alpha in temporal artery specimens among patients with GCA and dramatic benefit of TNF-inhibitors in other autoimmune diseases (e.g. rheumatoid arthritis) led to evaluation of TNF-alpha blockade in this condition." (PMID 30886946, 2017). "Similar findings have been reported in that although tocilizumab treatment decreased TNF-α and IL-1β levels, serum IL-6 levels were increased by tocilizumab therapy regardless of the improvements in clinical measures in rheumatoid arthritis patients." (PMID 27068103, 2016). "Epidemiologic data suggest that blockade of TNF-α has beneficial effects on vascular outcomes in patients with rheumatoid arthritis, however, detailed mechanistic studies are still lacking." (PMID 27467817, 2016). "Importantly, treatment of MSCs with rheumatoid arthritis synovial fluid (RASF), in which the concentrations of TNF were detected, modulated osteoclast generation in a close relation with the TNF level in RASF." (PMID 26823668, 2016). "According to EULAR recommendations, biologic DMARDs (bDMARDs) such as tumor necrosis factor inhibitor, tocilizumab (TCZ), and abatacept (ABT) are in parallel when prescribing to rheumatoid arthritis (RA) patients who have shown insufficient response to conventional synthetic DMARDs." (PMID 27435242, 2016). "Therefore, the identification of TNF-α and CCL2 antagonists from natural sources would represent a new approach for the management of various chronic inflammatory conditions, including rheumatoid arthritis and cardiovascular diseases like arthrosclerosis." (PMID 25878716, 2015). "The results from this study reveal that CD11c expression does not correlate with response to TNF inhibitor biologics when tested for within pre-treatment whole blood samples of rheumatoid arthritis patients." (PMID 26667261, 2015). "Accumulating evidences demonstrated that visfatin was identified as a proinflammatory adipocytokine and secreted extracellularly to upregulate inflammatory cytokines, such as TNF-α, IL-1β, IL-6 and CCL2 in rheumatoid arthritis synovial fibroblasts and monocytes in response to inflammatory stimuli." (PMID 25993304, 2015). "TNF-α plays a central role in most inflammatory responses and it is a validated target for drugs against a number of chronic inflammatory disorders resulting from immune dysregulations such as Crohn’s disease, ulcerative colitis, ankylosing spondylitis, rheumatoid arthritis (RA)." (PMID 25963543, 2015). "Treatment with TNF inhibitors is very efficient in the majority of the patients with rheumatoid arthritis (RA), but it does not achieve a sufficient treatment response in 40–50% of the cases." (PMID 26251236, 2015). "Abatacept is the only T cell co-stimulation modulator approved thus far for the treatment of moderate-to-severe rheumatoid arthritis (RA) and is licensed for use in patients with an inadequate response to methotrexate (MTX) and/or anti-tumor necrosis factor (anti-TNF) therapy." (PMID 28936386, 2015). "The treatment of rheumatoid arthritis (RA) and other forms of spondyloarthritis was revolutionized at the end of the 1990s, after the emergence of the so-called tumour necrosis factor alpha antagonists (anti-TNFα), which are biodrugs, also known as biopharmaceuticals, produced using biotechnology." (PMID 24980068, 2015).
rheumatoid arthritis (continued). "In rheumatoid arthritis (RA), there is of yet no genetic/genomic biomarker which can accurately predict response to TNF inhibitor biologics prior to treatment, despite much interest in this area." (PMID 26667261, 2015). "Additionally, TNFα has been shown to lead to FOXP3 dephosphorylation and consequent inhibition of Treg suppressive activity in rheumatoid arthritis patients." (PMID 25770018, 2015). "For example, iNOS-induced NO production following stimulation with proinflammatory cytokines, such as interleukin 1 (IL-1) and tumor necrosis factor-α (TNF-α), inhibits bone resorption and formation, resulting in osteoporosis in patients with inflammatory diseases such as rheumatoid arthritis." (PMID 26091235, 2015). "OPN −156G/GG did not affect the treatment response to anti-TNF therapy in patients with rheumatoid arthritis." (PMID 25161997, 2014). "Many patients with rheumatoid arthritis (RA) benefit from tumor necrosis factor-α blocking treatment (anti-TNF), but about one third do not respond." (PMID 24967817, 2014). "In fibroblast-like synoviocytes from rheumatoid arthritis patients, lipopolysaccharide induces an increase in TNF mRNA without TNF secretion due to miR-346 control." (PMID 24884781, 2014). "Many biological therapies are now available for patients with rheumatoid arthritis (RA) who have an inadequate response to synthetic disease modifying antirheumatic drugs (sDMARD) especially methotrexate (MTX) or to a first tumor necrosis factor (TNF) inhibitor (TNFi)." (PMID 24523570, 2014). "The treatment of rheumatoid arthritis (RA) in routine clinical practice comprises both biologic and non-biologic disease-modifying anti-rheumatic drugs (DMARDs), including methotrexate (MTX) and tumor necrosis factor (TNF) blocking agents." (PMID 24410774, 2014). "In the immune system, TNF-α is involved in the acute inflammatory response to stimuli, such as infection or tissue injury, and also plays a critical role in the pathogenesis of chronic inflammation and chronic inflammatory diseases, such as rheumatoid arthritis (RA) and Crohn’s disease." (PMID 24896264, 2014). "Treatment with an approved TNFα blocking antibody showed marked reduction in the levels of IL-6, IL-1β, and IL-17 and the expression level of STAT3 phosphorylation in relation to Th17 cell differentiation in patients with rheumatoid arthritis." (PMID 25436214, 2014). "Recently, we demonstrated Tumor Necrosis Factor alpha (TNF-α), and Bradykinin, respectively involved in rheumatoid arthritis and hereditary angioedema induced the cleavage of VE-cadherin ecto-domain (named soluble VE-cadherin or sVE, 90 kDa) in a Src dependent manner." (PMID 24358106, 2013). "We are not able to explain this biological phenomenon and it is also likely that this is not specific for Adalimumab neither for childhood uveitis, since other anti-TNF agents in different diseases (i.e. Rheumatoid Arthritis) can do the same." (PMID 23587261, 2013). "It has a marketing authorisation for use in combination with MTX for the treatment of moderate to severe active rheumatoid arthritis in adults whose disease has responded inadequately to previous therapy with one or more DMARDs, including MTX or a tumour necrosis factor (TNF) inhibitor." (PMID 23819062, 2013). "Etanercept (brand name, Enbrel), an anti-TNF-α agent, is a fusion protein of the human p75 TNF-α receptor attached to the Fc portion of human IgG1, which has been approved for the treatment of rheumatoid arthritis." (PMID 24373231, 2013). "The TNF-α monoclonal antibodies (infliximab, etanercept) used in the treatment of human autoimmune diseases (rheumatoid arthritis) have not been studied yet in neuropathic pain." (PMID 23956754, 2013). "Thus the use of anti-TNFα agents was demonstrated to be efficacious to achieve and keep clinical remission principally in IBD, rheumatoid arthritis, and psoriasis." (PMID 24063002, 2013).